PROS1 (protein S)
Diseases named in the same sentence as PROS1 in open-access papers (continued):
Sharing a sentence is not in itself a finding about the gene and the disease.
antiphospholipid syndrome (49 papers, 2006 to 2026). A disorder caused by the presence of autoantibodies directed against phospholipids, causing a hypercoaguable state, which may result in blood clots, stroke, heart attack, and in women, significant pregnancy-related complications, including miscarriage and still birth. "While previous reports have described challenges in managing CML in patients with other thrombophilic conditions, such as factor V Leiden or antiphospholipid syndrome, the coexistence of protein S deficiency presents unique therapeutic considerations." (PMID 40981007, 2025). "The CVT recurrence risk is higher in individuals with hereditary prothrombotic disorders, including factor V Leiden mutation, antiphospholipid syndrome, and deficiencies in protein C, protein S, or antithrombin." (PMID 41295442, 2025). "Through analysis of medical history, routine tests, and imaging examinations, the etiology of 38 patients: 8 cases of antiphospholipid syndrome, 6 cases with hematologic diseases, 3 cases of protein C deficiency, and 2 cases of protein S deficiency." (PMID 38886735, 2024). "The patient was diagnosed with HIT combined with protein S deficiency and antiphospholipid antibody syndrome." (PMID 39533629, 2024). "The majority of the women who develop atypical PE had pre-existing co-morbidities, mainly anti-phospholipid syndrome, pre-pregnancy hypertension, and protein S deficiency." (PMID 36835158, 2023). "Symptoms occurring at the anastomosis site due to inadequate venous drainage are similar to those related to IMV occlusion due to protein S or C deficiency or antiphospholipid antibody syndrome, such as mesenteric panniculitis of the colon or colitis." (PMID 36081545, 2022). "Late acute left atrial thrombosis is a rare life-threatening complication that mostly appears with predisposing primary coagulopathy, such as Protein C, Protein S, antithrombin 3 deficiency, antiphospholipid syndrome or hyperhomocysteinemia." (PMID 23286310, 2013). "Probable etiology is early carotid atherosclerosis associated with protein S deficiency in the first case and antiphospholipid syndrome in the second case." (PMID 22937467, 2011). "More patients in the cirrhosis only group had portomesenteric thrombus (SMV) (5/18) whereas almost half of the patients with bone marrow (BM) disorders, protein S deficiency, and anti-phospholipid syndrome (APS) had portosplenic thrombus (5/11)." (PMID 21658275, 2011). "A pathogenic role was identified for inherited deficiency of protein C, protein S and antithrombin and for inherited gene polymorphism of factor V Leiden and A20210G of prothrombin, and also for acquired thrombophilia, in particular antiphospholipid syndrome." (PMID 17625006, 2007). "The most commonly reported was homocystinaemia (12%), followed by anti-phospholipid syndrome (4%), mutations in Factor V Leiden (3%) and prothrombin (3%) genes, JAK2V617F mutation (1%), and antithrombin III (1%) and protein S (1%) deficiencies." (PMID 38068418, 2023). "The most common type was antiphospholipid syndrome (APLS; 14 (8%) patients), followed by protein S deficiency (12 (7%) patients)." (PMID 32351991, 2020). "We recommend that tPA activity and free-protein S levels be assessed in patients with autoimmune disorders with and without psychosis, especially those with lupus erythematosus or antiphospholipid antibody syndrome." (PMID 26731441, 2016). "Thrombophilia etiology divides into either heritable defects, such as mutations in the genes encoding the natural anticoagulants antithrombin, protein C, protein S, clotting factors, prothrombin, and factor V, or acquired defects, such as antiphospholipid syndrome (APS)." (PMID 39649503, 2024). "An autoimmune source of DVT could have been antiphospholipid syndrome where antibodies create complexes with anticoagulants such as antithrombin III, protein C, and protein S, thereby inactivating them and increasing the risk for thrombosis and embolism." (PMID 38975418, 2024).
antiphospholipid syndrome (continued). "Diagnostic workup revealed artery dissection (n = 4), rare arterial diseases (n = 3), autoimmune vasculitis (n = 1), hypoperfusion with bilateral watershed infarcts (n = 1), decreased protein S levels (n = 1), and antiphospholipid syndrome with positive test of anticardiolipin antibodies (n = 1)." (PMID 34867720, 2021). "Autoantibodies to Protein S have been documented in SLE and to Protein S and β2-glycoprotein 1 in SLE and anti-phospholipid syndrome." (PMID 30574119, 2018). "In the patients with antiphospholipid syndrome (APS), free protein S levels were not different from patients without a history of APS." (PMID 20637106, 2010).
viral infection (48 papers, 2010 to 2026). "Pre-pandemic literature on this topic has shown a relationship between viral infections and protein S and/or C deficiency among patients suffering from post-viral thrombotic complications." (PMID 39424883, 2024). "Idiopathic purpura fulminans (IPF) is a rare and severe coagulation disorder, associated with transient anti-protein S (anti-PS) antibodies in the context of post-viral infection such as varicella." (PMID 37325350, 2023). "This connection involves the individual susceptibility to viral infection, influenced by the expression of viral receptors and predisposition to coagulopathies, which may include potential mutations or functional alterations in PROS1." (PMID 38398746, 2024). "To investigate the effect of epithelium-derived PROS1 on the monocytes that accumulate in bronchial lumen upon viral infection, we performed cocultures of monocytes with ALI pseudostratified epithelium." (PMID 40980495, 2025). "Modulation of PROS1 in viral disease can therefore be a therapeutic target for protection against severe inflammation and airway damage." (PMID 40980495, 2025). "We found that basal cells expanded upon virus infection, and those cells expressed high levels of PROS1 mRNA." (PMID 40980495, 2025). "PROS1 reduced FOXJ1pos TPPP3pos deuterosomal cells and induced a small cluster of CXCL10pos basal cells at comparable levels to viral infection." (PMID 40980495, 2025). "It is well known that serum proteins such as Protein S and Gas6 enhance some enveloped-virus infections in macrophages." (PMID 35746720, 2022). "To confirm that AXL directly induces viral infection independently of its ligand GAS6 or Protein S in serum, we performed control experiments and found that GAS6 and Protein S are dispensable in AXL-induced SARS-CoV-2 virus pseudotype infection." (PMID 33420426, 2021). "Our studies revealed that Protein S and Gas6 mediate the binding step of virus infection by binding to envelope PtdSer and TAM receptors expressed on target cells." (PMID 31638994, 2019). "Studies of our and other research groups also showed that 1) Gas6 can mediate viral infection more efficiently than protein S and 2) Axl and Tyro 3 mediate viral infection more efficiently than Mer." (PMID 31638994, 2019). "We found that type III IFN-λ1 was elevated in the medium of cells at 72 hours post-infection, confirming active production of IFNs by our ALI cultures upon viral infection that could affect PROS1 secretion." (PMID 40980495, 2025). "In particular, vWF, HRG, PROS1, GC, F2, FGA, and FGB proteins, which are responsible for the expansion of vessels and new vessel formation, modulate blood coagulation and mitigate against vasoconstriction and coagulation caused by virus infection." (PMID 35401544, 2022). "On the other hand, specific viral structural proteins with highly conserved protein sequences, such as the spike RBD are expressed during viral infection." (PMID 38307890, 2024). "Knowing that viral infection induces IFN response from epithelium, we began by analyzing transcription factors downstream of IFN signalling that could bind the PROS1 promoter." (PMID 40980495, 2025). "The proportion of these cells was elevated for PROS1 supplementation alone and in the presence of SARS-CoV-2 and PROS1, but not in the presence of virus alone, showing that the MHC Class II gene upregulation is a strong feature of PROS1 signalling in monocytes regardless of viral infection." (PMID 40980495, 2025).
Stroke (36 papers, 2005 to 2026). Sudden impairment of blood flow to a part of the brain due to occlusion or rupture of an artery to the brain. "Herein, we present a rare case of a 40-year-old woman with ICVT and type II protein S (PS) deficiency, who experienced a stroke." (PMID 27193638, 2016). "Although deficiencies in protein C and protein S were observed in stroke patients with HIV, the question remains unclear whether these deficiencies are secondary events or directly caused by HIV infection." (PMID 32722629, 2020). "The pathogenic significance of increased protein S levels in men at high risk of CHD and stroke was unclear." (PMID 38879576, 2024). "We believe that metabolic investigations such as protein C, protein S, and anti-thrombin deficiency should be done, as well as determining S100β protein levels for post-CABG stroke and cerebral damage." (PMID 24217261, 2013). "The evidence we establish for a regulatory role of at least two SVZ endogenous VKDPs, protein S and Gas6, for neural precursors proliferation should be taken into account for the use of warfarin for treating stroke and cerebral ischemia." (PMID 22290807, 2012). "The other stroke patient had low protein S and activated protein C resistance, indicating the presence of factor V Leiden, which was confirmed by genetic testing (the patient was heterozygous for it)." (PMID 17640340, 2007). "There were no deaths in the CANA100 cohort; 1 death (due to a stroke secondary to protein S deficiency) was reported in the CANA300 cohort, which was not considered by the investigator to be related to the study drug." (PMID 32708943, 2020). "Therefore, it can be concluded that an increase in protein S concentration in platelets may indicate the presence of ischemic changes, as well as the occurrence of actions aimed at reducing the neurological deficit after a stroke." (PMID 35268287, 2022). "Most factors for which a sex difference was found, were measured 1–3 months after stroke (FVII, FXI, PAI-1, and Protein S) and are, therefore, not severely influenced by the acute phase of ischemic stroke." (PMID 34858141, 2021). "The aim of this work is to assess the role of hemorheological parameters (such as blood viscosity, hematocrit, platelet aggregation, and leukocyte count), protein C, protein S, antithrombin III, and serum albumin as predictors of stroke outcome." (PMID 30046235, 2018). "Fluid phase identification of inactive pre-MAC complexes with protein S such as sC5b-7, 8 and 9 in addition to VTN and CLU may also provide further information on the regulatory activity of the MAC in stroke survivors." (PMID 32849183, 2020). "Protein S deficiency and hyperhomocysteinaemia were associated with HIV infection, but not stroke in our study population." (PMID 28521833, 2017).
glioma (35 papers, 2005 to 2025). A benign or malignant brain and spinal cord tumor that arises from glial cells (astrocytes, oligodendrocytes, ependymal cells). "In contrast, the knockdown of PROS1 in human glioma cells (LN18) caused the activation of both extrinsic and intrinsic apoptotic pathways and the inhibition of migration and invasion." (PMID 37600806, 2023). "Increased expression of PROS1 was correlated with malignant phenotype and associated with poor prognosis in glioma." (PMID 36685506, 2022). "Yet, the comprehensive understanding of PROS1 on its expression level, clinical prognostic value, and its underlying mechanisms in gliomas is still unclear." (PMID 36685506, 2022). "The Spearman correlation analysis results suggested that the immune marker sets of Treg (FOXP3, CCR8, TGFβ1), TAM (CCL2, CD68, IL-10), and MDSC (CD33, ITGAM, FUT4) were significantly associated with the PROS1 expression in glioma." (PMID 36685506, 2022). "Furthermore, we found that the expression of PROS1 was negatively correlated with infiltration of M1 macrophage while positively associated with infiltration of M2 macrophage in glioma." (PMID 36685506, 2022). "All these findings proved that PROS1 expression could be associated with the malignant progression in glioma." (PMID 36685506, 2022). "In addition, increased PROS1 was associated with poor overall survival in glioma patients with IDH-Mut type, WHO G2&G3 grade, PR &CR,1p/19q non-codel, and astrocytoma." (PMID 36685506, 2022). "However, a comprehensive study on PROS1 expression, its prognostic value, and the underlying mechanisms in gliomas, especially in LGGs, is still missing." (PMID 35879775, 2022). "However, the prognostic significance of PROS1 in glioma and the underlying mechanism of PROS1 in shaping the tumor immune microenvironment (TIME) remains unclear." (PMID 36685506, 2022). "The level of PROS1 expression was significantly increased in glioma in comparison to normal tissue, which was further certificated by qRT-PCR and WB in LN-229 and U-87MG glioma cells." (PMID 36685506, 2022). "Kaplan –Meier survival analysis using data collected from TCGA indicated that the high expression of PROS1 was closely correlated with poor OS in glioma." (PMID 36685506, 2022). "Nevertheless, there are few types of researches focusing on the immune regulation of PROS1 in glioma., and the relevant knowledge is relatively poor." (PMID 36685506, 2022). "Consistent with the previous studies, through single -cell analysis and the results showed that PROS1 was closely correlated with invasion, metastasis, and proliferation of glioma cells." (PMID 36685506, 2022). "The results of the functional analyses demonstrated that PROS1 positively influenced cell invasion in two glioma single-cell sequencing datasets (BCH1126 and BCH836)." (PMID 35879775, 2022). "The high PROS1 group exhibited higher levels of the ImmuneScore, EstimateScore, and StromalScore than that of low PROS1 group in glioma." (PMID 36685506, 2022). "It is crucial for us to explore the fundamental roles and mechanisms of PROS1 in tumor progression and the correlation between PROS1 expression and immune microenvironment in glioma." (PMID 36685506, 2022). "The CancerSEA analysis demonstrated that PROS1 positively correlated with inflammation, invasion, metastasis, and proliferation in glioma." (PMID 36685506, 2022). "Functional analyses at the single-cell level showed that PROS1 was upregulated in glioma cells, promoting cell invasion." (PMID 35879775, 2022). "In order to confirm the significance of PROS1 in glioma, we discussed the correlation between PROS1 expression and clinicopathological parameters in glioma patients." (PMID 36685506, 2022). "Immune cell infiltration analysis showed that expression of PROS1 was negatively associated with pDC and NK CD56 bright cells while positively correlated with Macrophages, Neutrophils in glioma." (PMID 36685506, 2022).
glioma (continued). "Using quantitative PCR and western blot assay indicated that the protein and mRNA levels of PROS1 were significantly higher in glioma cells than in astroglia cells." (PMID 36685506, 2022). "In our study, through online database analysis, it was found that PROS1 expression level was significantly increased in glioma, and its high-expressions in LN-229 and U-87MG glioma cells were identified through the qRT-PCR and WB assay." (PMID 36685506, 2022). "Our multi-omics data results indicated that the expression of PROS1 in glioma had also increased significantly." (PMID 36685506, 2022). "The present study comprehensively analyzed the expression of PROS1 in glioma, its prognostic value and its immune regulatory effect in TME, to provide potential strategies for glioma immunotherapy." (PMID 36685506, 2022). "In conclusion, this study clarifies high PROS1 expression with the malignant phenotype and poor prognosis of glioma." (PMID 36685506, 2022). "TRIM38, CCR5, PLAU, P2RY8, and PROS1 were upregulated in glioma tissues, while HAMP and S100A9 were downregulated." (PMID 34954691, 2021). "In vitro experiments, knockdown of PROS1 could inhibit cells migration and proliferation of LN-229 and U-87MG glioma cells." (PMID 36685506, 2022). "Therefore, we downregulated PROS1 expression using small interfering RNA in the two glioma cell lines (LN-229, U-87MG)." (PMID 36685506, 2022). "Taken together, PROS1 may promote the progression of glioma by affecting migration and proliferation." (PMID 36685506, 2022). "Therefore, we furtherly comprehensive explored the relationship between PROS1 and immuno-modulatory in glioma." (PMID 36685506, 2022). "Moreover, we used single-cell analyses, GSEA analyses, GO,and KEGG pathway analyses to explore PROS1 functions in glioma." (PMID 36685506, 2022). "In addition, Increased expression of PROS1 was correlated with T-cell exhaustion, M2 polarization, poor Overall-Survival (OS) in glioma." (PMID 36685506, 2022). "The wound-healing assays and transwell assays showed that PROS1 knockdown could suppress the migration ability of glioma cells." (PMID 36685506, 2022). "And PROS1 was identified to be involved in the regulation of the immune response in glioma." (PMID 36685506, 2022). "The results showed that PROS1 promoted the malignant progress of glioma by shaping the micro-environment of immunosuppressive tumors, such as T cell failure, immunosuppressive cell infiltration, and the polarization of M1-type macrophages to M2 -type macrophages." (PMID 36685506, 2022). "ROC and KM curves were constructed to determine prognostic significance of PROS1 in glioma." (PMID 36685506, 2022). "Furthermore, we used single -cell analysis, GSEA, Go test and KEGG pathway analyses to investigate the roles of PROS1 in glioma, found that PROS1 was involved in the disease of the immune system and T cell antigen receptor pathway." (PMID 36685506, 2022). "As a result, increased PROS1 in glioma tissue could shape the micro-environment of immunosuppressive tumors to media its malignant progress." (PMID 36685506, 2022). "The area under the curve (AUC) of PROS1is 0.945 (95% CI: 0.935–0.955) and the best cut-off value of PROS1was 2.654, suggesting PROS1 may be a potentially moderate identification molecule for glioma patients." (PMID 36685506, 2022). "High expression of PROS1 positively correlated with inflammation, EMT, and invasion identified by CancerSEA, which was also proved by downregulation of PROS1 could suppress cells migration, and proliferation in LN-229 and U-87MG glioma cells." (PMID 36685506, 2022). "Protein S (PROS1), a known ligand of TAM (Tyro-3, Axl, and Mer) receptor tyrosine kinase family 102 is secreted by tumor-associated macrophages/microglia and associates with an activated AXL kinase in mesenchymal glioma stem cells." (PMID 32194848, 2020).